IL6 (interleukin 6)
Diseases named in the same sentence as IL6 in open-access papers (continued):
Sharing a sentence is not in itself a finding about the gene and the disease.
cholestasis (47 papers, 2012 to 2025). Impairment of the bile flow caused by obstruction within the liver, or outside the liver in the bile duct system. "For the first time, we demonstrated that it is not the extent but the duration of the elevation of the inflammation-associated proteins CrP and IL-6 that determines the risk of cholestasis and neurodevelopmental delay in this patient group regardless of the underlying disease, i.e., NEC, SIP or MI." (PMID 37049507, 2023). "According to a prior study, dexamethasone therapy restored the inflammation caused by cholestasis, as evidenced by histological findings and a significant decrease in many inflammatory markers (TNF-α, IL-1β, and IL-6)." (PMID 41517447, 2025). "Among them, TNF-α, IL-6, and IL-10 play important roles in inflammatory responses of the lungs after cholestasis." (PMID 39744639, 2024). "Our study confirmed these findings as infants with cholestasis showed a significantly higher incidence of CLABSIs, a greater need for re-laparotomies, higher maximum CrP values and a longer duration of CrP and IL-6 elevation after the initial surgery." (PMID 37049507, 2023). "There is a clear connection between elevated levels of interleukin 6 (IL-6) and the development of tumors, such as cholestasis, in patients with RCC." (PMID 37614277, 2023). "Inflammation in NASH and cholestasis is characterized not only by enhanced levels of IL-1ß but also by increased release of IL-6 and TNFα." (PMID 37175814, 2023). "CXCL8, NOS2, and IL-6 reportedly play a role in inflammation, hyperalgesia, cholestasis, and neoplastic cell transformation." (PMID 35720847, 2022). "The protective effects of fenofibrate and DCHT on ANIT-induced cholestasis and liver injury coincident with the inhibition of mRNA expression of inflammation-related genes (Il6, Il1b, and Tnfa), as well as the suppression of JNK/SAPK, NF-ĸB and STAT3 pathways." (PMID 35370715, 2022). "It was demonstrated that ANIT-induced cholestasis increased the levels of IL-1β, IL-6, and TNF-α and decreased the levels of IL-10." (PMID 36409145, 2022). "Cholestasis can trigger the release of cytokines such as IL-6, IL-1β, and TNF-α, which, in turn, repress NTCP transcription." (PMID 35495620, 2022). "The expression levels of serum inflammatory cytokines, such as tumor necrosis factor-α (TNF-α), interleukin (IL)-1β, and IL-6, are increased in patients with cholestasis, demonstrating that inflammation plays a role in cholestasis." (PMID 35924060, 2022). "On a molecular level, the pro-proliferative IL-6/AKT feedback loop was activated in Mir200c−/− livers but was inhibited in Sesn1−/− livers upon cholestasis in mice." (PMID 34880414, 2022). "To elucidate the pharmacological effects of KD on the alleviation of EE-induced cholestasis, we tested the protein expression of IL-1β and IL-6, known as pro-inflammatory cytokines, by Western blotting." (PMID 34064649, 2021). "Our data showed that IL-1β and IL-6 were prominently reduced in liver with EE-induced cholestasis by KD treatment." (PMID 34064649, 2021). "Various pro-inflammatory cytokines such as TNF-α and IL-6, which are activated in cholestasis, are responsible for this regulation." (PMID 34567144, 2021). "Our group has previously defined critical roles for the ADAM17-regulated cytokines TNFα and IL-6, cytokine receptor TNFRI, and immune cell adhesion molecule VCAM-1, in cholestasis associated sickness behavior development in BDL mice." (PMID 35095853, 2021). "Cholestasis is also an inflammatory disease characterized by elevated IL-1β and IL-6 levels in liver." (PMID 34064649, 2021). "In cholestasis, hepcidin levels go down, probably through suppression of interleukin 6 (IL6) induced STAT3 phophorylation by accumulated hydrophobic bile acids." (PMID 30134796, 2018). "Abnormal expression of IL-6, IL-10, IL-17A, IL-17F, TGF-β1 and α-SMA are closely associated with the cholestasis." (PMID 28646179, 2017).
cholestasis (continued). "IL-6 has been previously reported to involved in cholestasis among infants and children with intrahepatic and extrahepatic cholestasis." (PMID 27976737, 2016). "Pro-inflammatory cytokines such as TNF-α and IL-6 are mainly involved in cholestasis and the synthesis of acute-phase proteins." (PMID 26343741, 2015). "Levels of IL-6, TNF-α, IL-10, and IL-1β in liver tissue reflect the degree of hepatic inflammation caused by cholestasis, while serum levels of TC, TG, LDL-C, and HDL-C reflect lipid metabolism and oil red O staining visualizes lipid accumulation in liver tissue." (PMID 38523644, 2024). "Interestingly, CT_H was less effective than CF_L in reducing IL-6 and increasing IL-10 concentrations, suggesting an antagonism between the anti-inflammatory effects of the two drugs in the treatment of cholestasis." (PMID 38523644, 2024). "This demonstrates that the IL-6/AKT loop can be regulated by miR-200c/SESN1 during cholestasis." (PMID 34880414, 2022). "In cholestasis, TNFα mediates IL-6 release from macrophages to aggravate renal dysfunction." (PMID 34831270, 2021). "Similarly, CAR activation by TCPOBOP reduced cholestasis-induced liver dysfunction, inflammation (p65 nuclear translocation, mRNA expression of TNFα, IL-1β, IL-6) and oxidative stress." (PMID 34502180, 2021). "In support of this hypothesis, treatment with dexamethasone counteracted cholestasis-related hepatic inflammation by preventing NFκB translocation to the nucleus and restored TNFα, IL-6, and IL-1β mRNA levels in the liver of cholestatic rats." (PMID 33198224, 2020). "In addition, excessive production of TNF-α and IL-6 also leads to a decrease in bile flow, which further leads to cholestasis." (PMID 31827690, 2019). "Histological findings and a significant drop in several markers of inflammation (p65 nuclear translocation, mRNA expressions of TNF-α, IL-1β, IL-6) showed that DEX treatment reversed cholestasis-induced inflammation, and similar results have been obtained with oxidative stress markers." (PMID 30252871, 2018). "The decreased NTCP transport activities affect bile acids uptake might be due to increased IL-6 and TNF-α, which could partly explain cholestasis caused by SSd treatment, as noted in our study." (PMID 30034340, 2018). "Additionally, fenofibrate treatment recovered the increased inflammatory cytokines interleukin-1 (IL-1) and interleukin-6 (IL-6) in ANIT-induced cholestasis to the normal levels." (PMID 28855630, 2017). "IL-1β, IL-6, TNF-α, and IL-10 are common indices used to assess the inflammatory response, oxidative stress, and apoptosis, among others, in cholestasis." (PMID 36409145, 2022). "In the present study, cholestasis-induced inflammation in rats undergoing bile duct ligation was shown by the significant increase in serum levels of TNF-α, NF-ĸB and IL-6 pro-inflammatory cytokines compared to the control group." (PMID 34567144, 2021). "Together, considering that LIN28B/IL-6/STAT3 regulation seems to be an inflammatory loop-driven CCA initiation and able to explain the function of LIN28B in an early step of cholestasis -accelerated CCA in vivo." (PMID 34837926, 2021). "In this study, we examined the effects of VDR deletion in a mouse model of cholestasis and found that VDR-null mice show increased plasma bilirubin levels and reduced intestinal Il6 induction after BDL compared to wild-type mice." (PMID 23240054, 2012). "In our study, the levels of proinflammatory cytokines (TNF-α and IL-6) were decreased by MRS treatment, suggesting that MRS may attenuate liver injury in cholestasis via the reduced inflammatory response and macrophage infiltration." (PMID 31827690, 2019). "On the other hand, PE resveratrol and ginsenosides have been surprisingly reported as anti-cholestatic agents in the EE murine model, evidenced by reduced levels of biochemical markers of cholestasis, oxidative stress, as well as of the pro-inflammatory cytokines TNF-α, IL-6, and IL-1β." (PMID 31546715, 2019).
cholestasis (continued). "The disruption of the blood supply to liver cells as a consequence of cholestasis significantly contributes to the inhibition of the activity of protein biliary transporters, which may be reflected in elevated levels of TNF-α, IL-1β (interleukin-1β), and IL-6." (PMID 37834802, 2023). "In cholestasis, accumulated BAs result in the marked reduction of miR-200c and the subsequent increase of SESN1 in cholangiocytes, which contributes to the activation of the IL-6/AKT loop and increases ductular reaction, biliary hyperplasia, and biliary fibrosis." (PMID 34880414, 2022). "We do not exclude other mediators downstream of miR-200c in cholestasis and biliary liver fibrosis, but IL-6 can be regarded as a critical contributor to the hepatic damage in miR-200c-deficient BDL mice, given its prominent role in cholangiocyte proliferation and inflammatory responses." (PMID 34880414, 2022). "Interestingly, IL-6 was found to be higher in GWI than naïve rats even in the absence of cholestasis in animals that underwent sham surgeries." (PMID 30177688, 2018). "Interestingly, IL-6 was found to be elevated in GWI as compared to naïve in the groups subjected to sham surgery, suggesting that this particular cytokine was abnormally expressed due to only GWI-related chemical treatment, without cholestasis challenge." (PMID 30177688, 2018).
end-stage renal disease (47 papers, 2010 to 2026). "IL-6 levels predict the risk of developing incident CKD as well as CVD and mortality in patients with end-stage renal disease." (PMID 24683472, 2014). "In the other two papers, monocytes gene expressions in CKD and end-stage renal disease patients showed induction of the so-called suppressors of cytokine signaling, which modulate the Jak/Stat transcription pathway and steer the actions of IFNγ and IL6." (PMID 22957013, 2012). "It is well known that chronic inflammation is associated with elevated concentrations of proinflammatory cytokines, such as IL-1, IL-6, and TNF-α, in humans with end-stage renal failure." (PMID 37766698, 2023).
interstitial lung disease (47 papers, 2009 to 2025). A diverse group of lung diseases that affect the lung parenchyma. "Genetic variation in this gene has been associated with interstitial lung disease and with circulating levels of IL-6, a pro-inflammatory cytokine with higher levels in COPD." (PMID 36681830, 2023). "A different study involving a large cross-sectional cohort of SSc patients and healthy donors also underlined the link between interstitial lung disease and elevated serum IL-6." (PMID 37833885, 2023). "High WBC, CRP, and IL-6 levels in patients with acute exacerbation of interstitial lung disease are known to be associated with the patient’s prognosis." (PMID 35566611, 2022). "Elevated levels of IL-6 (> 25.20 pg/mL) have been identified as an independent risk factor for acute exacerbation (OR 1.014 [95% CI 1.001–1.027], p = 0.036) and death (OR 1.007 [95% CI 1.001–1.014], p = 0.018) in patients with interstitial lung disease." (PMID 37951977, 2023). "IL-6 levels are elevated in the sera of SSc patients and have been shown to be strongly associated with the severity of skin thickening and disease progression in interstitial lung disease." (PMID 37109064, 2023). "Our results suggest that increased interleukin-6 levels in the blood following tocilizumab treatment may be linked to development of interstitial lung disease." (PMID 34496961, 2021). "Similar to prior reports, we observed an association of IL-6 with interstitial lung disease." (PMID 19799786, 2009). "Increased levels of IL-6, which can be found in the sera and skin of SSc patients, correlate with disease severity, in particular with the extent of skin and pulmonary involvement, and they can also predict SSc-linked interstitial lung disease (ILD), decline and mortality." (PMID 40141068, 2025). "Elevated levels of IL-6 and TNFα have indeed been reported in the serum of SSc patients in several studies, and both cytokines are associated with fibrotic processes, disease progression, and the occurrence of interstitial lung disease, especially in dcSSc patients." (PMID 33922041, 2021). "on patients with interstitial lung disease, using a program with an amplitude of 4–6 mm and a frequency of 6–26 Hz, revealed a reduction of −1 pg/mL in serum IL-6 levels in the intervention group, while the control group remained unchanged." (PMID 41293158, 2025). "Patients with higher circulating IL-6 were more likely to have interstitial lung disease (odds ratio = 1.33, 95% confidence interval = 1.08 to 1.62)." (PMID 19799786, 2009). "Additionally, they can mediate induction of different cytokines, such as MCP-1 and interleukin-6 (IL-6), and they contribute to interstitial lung diseases." (PMID 41441980, 2025). "Interleukin-6 (IL-6) is hypothesised to be associated with the pathogenesis of irAEs, including ICI-related interstitial lung disease (ILD)." (PMID 38414933, 2023). "STAT family of proteins can activate the expression of many survival-related genes, including BCL2, HIF-α, VEGF and IL-6, that play an important role in interstitial lung diseases via stimulating survival, proliferation, angiogenesis and migration and resisting autophagy." (PMID 37242480, 2023). "Similarly, subjects with interstitial lung disease were found to have higher levels of IL-6, TNF-α, TGF-β, IFN-γ and other inflammatory cytokines." (PMID 33802067, 2021). "Furthermore, serum cytokine profiles are also similar in these two conditions, such as serum levels of ferritin, IL-6, IL-8, and IL-10 usually were elevated in patients with severe COVID-19 and rapid progressive interstitial lung disease (RP-ILD) secondary to anti-MDA5 Ab-related DM." (PMID 34987516, 2021). "High IL-7 levels were characteristic of SSc-associated interstitial lung disease (ILD) and, in addition, when compared with ILD-negative SSc patients, ILD-positive SSc patients revealed higher IL-4, IL-6, IL-8, and CCL2 (MCP-1) BALF levels." (PMID 19615053, 2009).
interstitial lung disease (continued). "Tocilizumab, an IL-6 inhibitor, has been FDA approved for the treatment of interstitial lung disease in SSc, especially effective in the inflammatory phase of disease (patients with high C-reactive protein)." (PMID 37372943, 2023). "Enhanced IL-6 signaling has been shown to contribute to interstitial lung disease (ILD) pathogenesis, through the IL-6/STAT3/IL-17A signaling pathway." (PMID 36543914, 2022). "Furthermore, the high level of IL-6 is related closely to interstitial lung disease (ILD), a complication of SS." (PMID 35990826, 2022). "Serum IL-18, IL-6, IL-10, and IFN-β were increased in DM patients with interstitial lung disease as well." (PMID 32644977, 2020). "Furthermore, thalidomide reduces lipopolysaccharide‐stimulated release of TNF‐α, IL‐8, and IL‐18 (‘necrotic’ cytokines), but not IL‐6, IL‐10, and IL‐12 (p70) (‘inflammatory’ cytokines) from alveolar macrophages in patients with interstitial lung disease." (PMID 38481033, 2024). "A positive correlation, even though not as strong, could be observed between pulmonary interstitial disease and IL-6 serum levels (r = 0.5738, p < 0.0052, Pearson’s correlation test)." (PMID 38398414, 2024).
pulmonary TB (47 papers, 2011 to 2026). "Our discovery-validation analyses among geographically and epidemiologically diverse populations of pulmonary tuberculosis cases found an association between higher baseline IL-6 concentrations in plasma and subsequent treatment failure, recurrence and death." (PMID 34711538, 2022). "It has been found that variants of IL1B were associated with latent tuberculosis infection, whereas variants of IL6 and TNFα variants were associated with pulmonary tuberculosis." (PMID 35153741, 2021). "In addition to its previously identified role as a biomarker of active pulmonary TB, we found that increased IL-6 expression at active disease is significantly associated with faster bacterial clearance." (PMID 33868272, 2021). "Pulmonary TB is driven by persistent inflammation, involving pro-inflammatory cytokines such as tumor necrosis factor-alpha, interleukin-6 and interferon-gamma." (PMID 40978039, 2025). "Changes in the serum levels of the proinflammatory cytokines TNF-α, IL-6, and IL-1β in the two groups of pulmonary tuberculosis patients before and after antituberculosis treatment were detected via ELISA." (PMID 40129950, 2025). "Macrophages are generally considered a major source of IL-6 during chronic inflammatory processes, including pulmonary TB." (PMID 36674664, 2023). "Increased IL-6 levels measured in bronchoalveolar lavage (BAL) of patients with pulmonary TB were shown to correlate with lung cavitation." (PMID 37653422, 2023). "miR-365 regulates IL-6 production in macrophages, leading to the immune response in pulmonary tuberculosis." (PMID 35128217, 2022). "In pulmonary TB, the high concentrations of IL-6/IL-10 and STAT-3 led to the impaired function of T cells." (PMID 36439164, 2022). "Summarizing, a complete abrogation of IL-6-dependent immune reactions during TB course looks rather detrimental, and in patients with pulmonary TB IL-6 levels in sera are elevated compared to healthy donors." (PMID 35154093, 2022). "Few studies revealed increased IL-6 concentrations in sera of patients with far-advanced pulmonary TB compared to healthy subjects and elevated level of il6 expression in peripheral blood cells from TB patients." (PMID 35154093, 2022). "Quantitative measurements by rapid UCP-LFAs specific for SAA1, IP-10, and IL-6 in serum can be utilized to detect active progressive pulmonary TB in macaques." (PMID 34943175, 2021). "Conversely, miR-365 expression was significantly lower in alveolar macrophages from patients with active pulmonary TB as compared to healthy controls, which inversely correlated with IL-6 heightened expression." (PMID 30941122, 2019). "It was also reported that miR-365 regulates IL-6 expression via the MAPK/ERK pathway in HEK293 and Hela cells, while enhanced expression of IL-6 in macrophages of patients with pulmonary tuberculosis is associated with downregulation of miR-36544,45." (PMID 29263346, 2017). "We also found that IL-6 enhances inflammatory cytokine production in pulmonary tuberculosis patients with T2DM." (PMID 27783671, 2016). "We also found that IL-6 increases inflammatory cytokine production in pulmonary tuberculosis patients with T2DM." (PMID 27783671, 2016). "Compared with healthy donors, the peripheral blood plasma of pulmonary tuberculosis patients contained significantly higher levels of IL-6 and IL-9." (PMID 23028695, 2012). "The objective of the current study was to analyze IFN-γ gene combinations with other IFN-γ regulating cytokine genes (IL-10, TNF –α, IL-6) to see the effect of gene- combinations on disease severity outcome in pulmonary tuberculosis." (PMID 22140472, 2011). "Some studies have reported increased concentrations of IL-6 in the sera of patients with advanced pulmonary TB compared to healthy controls, as well as elevated IL-6 gene expression in peripheral blood cells of TB patients, supporting a potential pathophysiological role." (PMID 39963138, 2025).